KRT12 (keratin 12)
Description:
Structural component of intermediate filaments in the corneal epithelium. Forms heteropolymers with the type II keratin KRT3, assembling into keratin intermediate filament networks that provide mechanical strength and structural integrity to the corneal epithelial layer.
Synonyms: K12; MECD1
Tractability: PROTAC: ubiquitination databases record sites on it.
Gene: Protein-coding gene on chromosome 17 (40,861,303 to 40,867,223, reverse strand). Ensembl gene ENSG00000187242.
Pathways (Reactome):
Developmental Biology: Formation of the cornified envelope; Keratinization
Gene Ontology:
Molecular function: structural constituent of skin epidermis; structural molecule activity
Biological process: cornea development in camera-type eye; morphogenesis of an epithelium; epithelial cell differentiation; intermediate filament organization; visual perception
Cellular component: extracellular exosome; cytoskeleton; cytosol; keratin filament
Genetic constraint (gnomAD): Loss-of-function variants: 33 observed, 45.08 expected, observed/expected ratio (o/e) 0.73, 90% interval 0.55 to 0.98. The upper end of that interval is the gene's LOEUF score, 0.98, which puts it in group 4 of 6, group 1 being the genes least tolerant of losing a copy. Missense variants: 522 observed, 592.87 expected, observed/expected ratio (o/e) 0.88, 90% interval 0.82 to 0.95. Synonymous variants: 237 observed, 245.14 expected, observed/expected ratio (o/e) 0.97, 90% interval 0.87 to 1.08.
Homologues: Orthologues: chimpanzee KRT12 (99% identical), macaque KRT12 (98% identical), dog KRT12 (85% identical), rabbit KRT12 (85% identical), mouse Krt12 (78% identical), rat Krt12 (78% identical), pig KRT12 (76% identical), tropical clawed frog krt12.6 (52% identical), tropical clawed frog krt12.3 (51% identical), tropical clawed frog krt53 (50% identical), tropical clawed frog krt12.2 (48% identical), tropical clawed frog krt51 (45% identical), and 1 more. Paralogues in human: KRT24 (54% identical), KRT10 (52% identical), KRT14 (52% identical), KRT16 (52% identical), KRT15 (50% identical), KRT17 (50% identical), KRT13 (49% identical), KRT19 (47% identical), KRT27 (46% identical), KRT28 (46% identical), KRT26 (45% identical), KRT25 (44% identical), and 56 more.
Diseases named in the same sentence as KRT12 in open-access papers:
KRT12 is named in the same sentence as 25 diseases in open-access papers, as found by Europe PMC text mining. Sharing a sentence is not in itself a finding about the gene and the disease. The quoted sentences say what the papers report.
Meesmann corneal dystrophy (10 papers, 2007 to 2026). Meesmann corneal dystrophy (MECD) is a rare form of superficial corneal dystrophy characterized by distinct tiny bubble-like, round-to-oval punctate bilateral opacities in the central corneal epithelium, and to a lesser extent in the peripheral cornea, with little impact on vision. "Krt8/keratin 8 was shown to protect against degeneration of retinal pigment epithelium under oxidative stress, and KRT3 and KRT12 gene mutations associated with Meesmann corneal dystrophy." (PMID 35118070, 2021). "A dominant-negative mutation in KRT12,187 which causes Meesmann epithelial corneal dystrophy (MECD), results in the occurrence of a novel Streptococcus pyogenes PAM." (PMID 32296011, 2020). "Heterozygous mutations in KRT12 cause Meesmann's corneal dystrophy, an autosomal dominant disorder that affects corneal epithelium." (PMID 23533700, 2013). "We have identified a novel missense mutation within the highly conserved helix-initiation motif of KRT12 causing Meesmann`s corneal dystrophy in a German family." (PMID 20577595, 2010). "All known mutations in the cornea specific genes KRT3 and KRT12 are responsible for the development of Meesmann`s corneal dystrophy, an autosomal dominant disorder of the corneal epithelium." (PMID 20577595, 2010). "We have identified a novel mutation in the KRT12 gene that is associated with a symptomatic phenotype of Meesmann's corneal dystrophy." (PMID 17653038, 2007). "In conclusion, this study provides the first evidence that the co-occurrence of variants in two Meesmann corneal dystrophy-associated genes (KRT3 and KRT12) can jointly account for the disease phenotype." (PMID 41683752, 2026). "Disruption of Krt12 gene results in fragile corneal epithelium resembling Meesmann's corneal dystrophy in the mouse." (PMID 23533700, 2013). "The only known disorder associated with mutation in cornea-specific keratin 3 (KRT3) and keratin 12 (KRT12) representing type II and I intermediate filaments, respectively, is Meesmann corneal dystrophy (MCD)." (PMID 18806880, 2008).
corneal dystrophies (4 papers, 2009 to 2020). "Although mutations in genes such as KRT3, KRT12, PIP5K3, TGFBI, and UBIAD1 have been associated with specific corneal dystrophies, genes associated with all corneal dystrophies have yet to be identified." (PMID 32823625, 2020).
pterygium (3 papers, 2009 to 2025). A wedge-shaped fibrovascular lesion arising from the bulbar conjunctiva and extending to the cornea. "KRT12 mRNA expression in corneal epithelial samples was significantly lower in pterygium samples than in controls (p = 0.001)." (PMID 40094891, 2025). "In the pterygium there was a patchy distribution of both Krt12 and 13 up to a normal corneal epithelial region specific for Krt12." (PMID 19956562, 2009). "The expression pattern of keratins and other markers in pterygium most closely resemble those of conjunctival and limbal cells; some corneal markers are present, notably Krt12, but at lower levels than equivalent conjunctival markers." (PMID 19956562, 2009). "Principal component analysis in pterygium indicated a signature of matrix-related structural proteins, including fibronectin-1 (both splice-forms), collagen-1A2, keratin-12 and small proline rich protein-1." (PMID 19272163, 2009). "Since EBMD, SND and pterygium lead to changes in the corneal epithelium, we analyzed levels of the corneal keratins KRT3 and KRT12, as well as the conjunctival keratin 13 (KRT13) in our samples." (PMID 40094891, 2025). "In this context, we compared the expression of corneal keratins KRT3, KRT12, and KRT13 in EBMD, SND, and pterygium." (PMID 40094891, 2025).
aniridia (2 papers, 2013 to 2021). Aniridia is a congenital ocular malformation characterized by the complete or partial absence of the iris. "KRT3 and KRT12 markers are downregulated in ocular surface of subjects with aniridia and are described as being regulated by PAX6 in vitro as well." (PMID 34827649, 2021).
corneal ulcer (2 papers, 2016 to 2022). Area of epithelial tissue loss from corneal surface; associated with inflammatory cells in the cornea and anterior chamber. "The lack of severe epithelial defects such as corneal ulceration and perforation in the Krt12 null mice was attributed to the rapid replacement of lost superficial epithelial cells from deeper layers." (PMID 26758872, 2016).
dry eye (1 paper, 2017). "Accordingly, we show that SS-associated dry eye-mediated denervation of the chronically inflamed cornea is accompanied by increased proliferation of corneal epithelial basal cells and altered differentiation of KRT19-positive progenitor cells to their KRT12-positive corneal lineage." (PMID 28926640, 2017).
epithelial corneal dystrophies (1 paper, 2016). "This is the first MECD model to carry a mutation within the KRT12 gene that is known to cause MECD in man and as such will provide an in vivo model in which to test potential therapies for epithelial corneal dystrophies." (PMID 26758872, 2016).
myopia (1 paper, 2019). "Our microarray data also shows that three of these genes are expressed in human fetal eye tissues (ARL1, KRT12, and PQLC1), of which two (PQLC1 and KRT12) are also expressed in a mouse model of myopia, leading to the hypothesis that these CpG sites may be biologically relevant." (PMID 31100065, 2019).
cancer (2 papers, 2021 to 2022). A tumor composed of atypical neoplastic, often pleomorphic cells that invade other tissues. "We also checked expression of EMT markers, such as E-Cadherin, Krt12, Vimentin, Survivin, Slug, ZEB1 and ZEB2, in the TNBC cancer cells, and found that expression of ZEB1 was positively correlated with expression of SENP1." (PMID 35342335, 2022).
neurological disease (1 paper, 2017).
tumor (1 paper, 2024). "Mutations in KRT12 consist of dominant in-frame insertion in tumor samples from White patients." (PMID 38637560, 2024).
KRT12 also shares sentences with these, for which no sentence is quoted: infection (5 papers); tauopathies (2); viral infection (2); congenital stromal corneal dystrophy (1); fleck corneal dystrophy (1); Fuchs endothelial corneal dystrophy (1); fungal keratitis (1); gelatinous drop-like corneal dystrophy (1); leishmaniasis (1); macular corneal dystrophy (1); posterior polymorphous corneal dystrophy (1); Schnyder corneal dystrophy (1); staphylococcus aureus infection (1); Stevens-Johnson syndrome (1).